EGFR (epidermal growth factor receptor)
Diseases named in the same sentence as EGFR in open-access papers (continued):
Sharing a sentence is not in itself a finding about the gene and the disease.
cancer (continued). "Osimertinib is one of the FDA-approved anti-cancer therapies/EGFR inhibitors." (PMID 40733034, 2025). "Notably, EGFR mutations, such as the L858R mutation commonly found in non-small cell lung cancer (NSCLC), present unique challenges for cancer subtype diagnosis." (PMID 40906195, 2025). "Subsequently, we could show that the intact complex is a potent EGFR inhibitor itself, which efficiently transports the platinum inside the cancer cells." (PMID 39801772, 2025). "This framework could explain why some cancers with EGFR overexpression show limited response to EGFR inhibitors if concurrent glycosylation changes have already redirected signaling through alternative routes." (PMID 41446266, 2025). "IgA mAb against EGFR were ineffective against PDAC cell lines, suggesting that the antigen density on PDAC cell lines (<150,000) was too low to induce ADCC with neutrophils, especially considering that EGFR IgA mAbs are effective against other cancer cell lines." (PMID 40358156, 2025). "Through the coordination with membrane-associated glycoproteins—including CD44, epidermal growth factor receptor (EGFR), integrins, CD280 (uPARAP/Endo180/MRC2), and CD276, CD147 orchestrates intracellular signaling events that drive cancer cell metabolic adaptation." (PMID 41479915, 2025). "Random forest model showed the promising results in identifying EGFR biomarkers in cancer patients." (PMID 40078179, 2025). "We speculated that, in these patients, gefitinib-sensitive cancer cells are mostly inhibited by the EGFR-TKI, while chemotherapy acts on the subpopulations of resistant cells capable of growing in the presence of gefitinib." (PMID 40846697, 2025). "The development of inhibitors targeting mTOR or EGFR has notably advanced cancer therapy." (PMID 40259053, 2025). "Overexpression of both MET and EGFR is commonly found in the same malignant tumor, such as CRC." (PMID 39941081, 2025). "EGFR plays a crucial role in both cancer and immune diseases." (PMID 39966897, 2025). "Owing to its crucial role in cancer progression, a range of EGFR-targeted therapies have been developed, including humanized monoclonal antibodies that bind to its extracellular domain and selective small-molecule inhibitors that block its tyrosine kinase domain." (PMID 41488515, 2025). "This indicates that the polyR peptide, or an analog, could potentially serve as a therapeutic agent in EGFR-related cancers." (PMID 40449599, 2025). "Thus, modulation/inhibition of EGFR activity is an appealing target of developing novel cancer therapeutics." (PMID 41174103, 2025). "Furthermore, since TNS4 modulates activated EGFR levels and acts as a downstream effector in the Ras/Raf/Mek/MAPK cascade, combinatorial targeting of TNS4 and EGFR represents a theoretically viable strategy for EGFR-dysregulated cancers." (PMID 40906372, 2025). "Notably, EGFR upregulation in cancer frequently leads to hyperactivation of pro-oncogenic pathways like RAS-RAF-MEK-ERK MAPK and AKT-PI3K-mTOR." (PMID 40906372, 2025). "LAPTM4B, an oncoprotein that promotes active EGFR signaling in cancer cells and is required for the autophagy process induced by inactive EGFR, might represent a synergistic targeting molecule in cancer therapy." (PMID 40231269, 2025). "Indeed, by phenotyping tumors according to relevant gene set expression scores, we show that RNA VAF identifies instances of possible driver-passenger misclassification events within the cancer genes EGFR and KDM6A." (PMID 40514689, 2025).
cancer (continued). "In this study on EGFR mutation status, significant findings include that Stage III patients are significantly more likely to exhibit positive EGFR mutations with an odds ratio (OR) of 11.07 (p = 0.021), suggesting advanced cancers are more mutation-prone." (PMID 40502411, 2025). "From the perspective of managing adverse events in patients undergoing cancer treatment, prophylactic therapy should be applied to high‐risk patients with FAfR rather than to all patients treated with EGFR inhibitors." (PMID 40503645, 2025). "Researchers found a correlation between an increased level of the specific protein Epidermal Growth Factor-like repeats and Discoidin I-Like Domains 3 (EDIL-3) and cancer angiogenesis and migration, mediated via epidermal growth factor receptor (EGFR) activation." (PMID 40006624, 2025). "Targeting EGFR using Se-products has shown promise in treating cancer." (PMID 38739230, 2025). "miR-126 prevents cancer cells from multiplying and invading nearby tissues by downregulating EGFR." (PMID 40227645, 2025). "Our findings raise the question of whether fluctuations in serum CEACAM5 reflect EMT and rEMT processes in both primary tumors and metastatic sites, contributing to cancer dissemination and drug resistance under EGFR‐TKI treatment." (PMID 40856433, 2025). "Our method may resolve the critical limitation of EGFR-based cancer diagnostics, that is, the confounding effects of morphological changes that occur during prolonged capacitance measurements." (PMID 41294763, 2025). "Additionally, ω-3 PUFAs alter membrane lipid rafts and receptor signaling: DHA/EPA enrichment in cancer cell membranes disrupts EGFR localization, which in turn impairs downstream PI3K/Akt signaling." (PMID 40808836, 2025). "We hypothesized that using this library for selection against overexpressed cancer receptors like EGFR could generate fine-tuned binders enabling new treatment regimes." (PMID 41289384, 2025). "As such, EGFR inhibitors (EGFRIs) are increasingly used in cancer precision therapies." (PMID 39924511, 2025). "This suggests that inhibiting the ER export of EGFR could represent a novel strategy for downregulating its activity in cancer treatment." (PMID 40449599, 2025). "By examining how silibinin affects EGFR‐mediated pathways, we can further elucidate the comprehensive mechanisms by which silibinin exerts its antitumor effects, paving the way for more targeted and effective cancer treatments." (PMID 39907159, 2025). "Epidermal growth factor receptor (EGFR) is an important target for anti-cancer therapies." (PMID 39838173, 2025). "In addition to its relevance as a therapeutic target, EGFR stands among the most targeted receptors for cancer active targeting." (PMID 39940134, 2025). "Multivariable analysis showed that shorter overall survival was independently associated with socioeconomic deprivation, EGFR L858R mutations, distant disease at cancer diagnosis, and non-Asian or non-Pacific ethnicities." (PMID 40029742, 2025). "The ineffectiveness of EGFR inhibitors is due to the attempt to remove from the cell an enzyme that plays an important role in many biochemical and biological functions, to which cancer cells respond by creating drug-resistant mutants." (PMID 40700134, 2025). "We systematically reviewed the Hub-EGFR.Sig scores in TCGA pan-cancer datasets." (PMID 40574864, 2025). "The inhibition of EGFR was reported to inhibit the activity of E2F1 in cancers." (PMID 41155666, 2025). "Therefore, we comprehensively screened the immune molecular landscape of EGFR.Sig across various cancers." (PMID 40574864, 2025). "EGFR signaling is known to drive dysregulated FA metabolism, and influence lipid membrane composition and saturation to modulate tolerance to reactive oxygen species (ROS) and cancer cell survival." (PMID 40710558, 2025).
cancer (continued). "Indeed, previous studies have leveraged antibody or antibody combinations to overcome acquired resistance in other cancer settings, such as in the case of EGFR." (PMID 40014401, 2025). "Blocking EGFR signaling could increase susceptibility to FAS-mediated apoptosis, making it a promising therapeutic target in cancer." (PMID 41188939, 2025). "Notably, pembrolizumab and nivolumab, previously discussed as monoclonal antibodies, overlap with this category, as they release the brakes on T cells and are very effective against oncogene-driven cancers that have mutations in genes like KRAS and EGFR." (PMID 40149342, 2025). "Analogies with other cancers, with oncogenes such as Myc, EGFR, HER2, PI3Kca and so on, may be useful." (PMID 41446211, 2025). "In cancer treatment, some substances specifically block EGFR reaction pathways." (PMID 39561105, 2025). "Finally, we showed that osimertinib, an anti-cancer drug/EGFR inhibitor, blocked EGF-stimulated OAT3 transport activity." (PMID 40733034, 2025). "Moreover, protein levels determined via Western blot confirmed that the EGFR/AKT/ERK pathway stops the proliferation of cancer cells." (PMID 40172364, 2025). "Targeting the EGFR signaling pathway has emerged as a key approach in cancer therapy." (PMID 41488515, 2025). "Using elegant precedence of ganglioside-mediated activation of growth factor receptor signaling, our work reveals that increased GD3 gangliosides in response to altered expression of UGCG boost the EGFR phosphorylation status and subsequent downstream growth signaling in luminal cancers." (PMID 40934285, 2025). "Evidence exists in other cancers demonstrating EGFR activity is needed for full activation of MEK and ERK downstream of mutant KRAS and this may be the first example of that in NSCLC, reinforcing a need to target BACE1 in this setting." (PMID 40601773, 2025). "Furthermore, HER2 has been found to be co-expressed with EGFR in HNSCC tumors, where EGFR is a protein that helps cells grow, and mutations in the EGFR gene can cause cancer cells to grow too quickly." (PMID 40430804, 2025). "By providing a computational framework for correcting morphology-induced measurement errors, our method improves the precision and reliability of EGFR-based cancer diagnostics, potentially contributing to improved cancer detection and characterisation methodologies." (PMID 41294763, 2025). "Combinatorial therapeutic approaches targeting both EGFR and MET have been tested clinically—predominantly in the context of EGFR-driven cancers with MET-mediated acquired resistance—and have shown promising results, supporting the benefit of this approach for NSCLC treatment." (PMID 39858062, 2025). "EV‐mediated EGFR signaling is important to EGFR‐driven cancers." (PMID 40470380, 2025). "Notably, EGFR activation has been shown to induce PKM2 translocation into the nucleus in human cancer cells." (PMID 39841618, 2025). "We further tested all these mutations in 367 NSCLCs lacking driver mutations and 184 carcinomas carrying activating mutations in EGFR or KRAS genes." (PMID 40661875, 2025). "Consequently, the pursuit of targeting the EGFR TK allosteric site has emerged as a very desirable technique for cancer treatment." (PMID 39404419, 2024). "Building on Stanley Cohen’s discoveries in the 1960s regarding the EGFR’s connection to malignancy, Dr. John Mendelsohn expanded this research in the 1980s and proposed that blocking EGFR signaling could serve as an effective anti-cancer treatment." (PMID 39337496, 2024). "Combining EGFR inhibition with targeting ENAH signaling could potentially improve the response rates to cancer treatments." (PMID 39511483, 2024). "EGFR is often found to be constitutively activated in human cancer." (PMID 38492569, 2024).
cancer (continued). "The results of this study and the analysis highlight the binding affinities of these ligands against key proteins involved in cancer pathways: Epidermal growth factor receptor (EGFR, PDB ID: 1XKK), aromatase (PDB ID: 3S7S), and phosphoinositide 3-kinase alpha (PI3K alpha, PDB ID: 7PG6)." (PMID 40066125, 2024). "In in vivo experiments, EGFR-KD markedly reversed ADAMTS1-induced dissemination of cancer cells." (PMID 39333870, 2024). "This structural similarity and interaction suggest that BNS3 may also exhibit potent EGFR inhibition and could offer enhanced efficacy in treating cancers with EGFR involvement." (PMID 39338272, 2024). "In GBM, besides EGFR amplifications and mutations, IDH mutations and PTEN loss stand out as some of the most extensively investigated genetic drivers influencing the regulation of cancer cell metabolic reprogramming." (PMID 39538085, 2024). "In addition to impacting the growth of cancer cells, the activation of EGFR also promotes the formation of new blood vessels (angiogenesis)." (PMID 39569013, 2024). "This suggests a relationship between the EGFR signaling pathway and important processes such as cell proliferation, metastasis, angiogenesis (formation of new blood vessels), and apoptosis (programmed cell death) in the context of cancer." (PMID 38828424, 2024). "However, cancer cells can develop drug resistance during long-term treatments, which diminishes the effectiveness of EGFR inhibitors." (PMID 39897079, 2024). "Moreover, the EGFR/ErbB2 dimer is involved in steps that are crucial for cancer progression, such as cell proliferation, migration and invasiveness." (PMID 38370412, 2024). "EGFR is closely related to cancer cell proliferation, apoptosis, and metastasis." (PMID 38606171, 2024). "EGFR activation triggers two key signaling cascades in cancer: the PI3K/AKT/mTOR and MAPK pathways." (PMID 39126121, 2024). "The concomitant targeting of EGFR and autophagy might offer a window of opportunity to combat survival advantage and drug resistance in cancer treatment." (PMID 38764025, 2024). "Epidermal growth factor receptor (EGFR) signaling is a frequent event in cancer development." (PMID 38342905, 2024). "Then, they showed that directly targeting diverse cancer driver mutations, including EGFR, ALK, and RAS, as well as their downstream signaling pathways, could prime cancer cells for destruction by macrophages and remodel macrophage polarization." (PMID 38690738, 2024). "Furthermore, the review discusses the clinical applications of FDA-approved EGFR inhibitors such as erlotinib, gefitinib, afatinib, and osimertinib across various cancer types and their corresponding clinical outcomes." (PMID 38611728, 2024). "The therapeutic approach in NSCLC depends on the presence or absence of specific mutations, which in this type of cancer occur most frequently in the EGFR or KRAS gene." (PMID 39457707, 2024). "The epidermal growth factor receptor (EGFR), is deeply involved in HNC onset and development: according to the recent statistics, more than 90% of all HNC display an EGFR overexpression; moreover, high EGFR levels are inversely correlated with poor prognosis and cancer's patient survival." (PMID 38169656, 2024). "Additionally, activation of the EGFR-RAS–RAF–MEK-MAPK cascade promotes cancer cell proliferation, survival, migration and angiogenesis through the transcriptional regulation of related genes." (PMID 39469460, 2024). "Upregulation or high activation of EGFR is frequently found in many human cancers." (PMID 38164181, 2024). "However, even with the highly effective third generation of EGFR inhibitors, their anticancer effects can gradually diminish, and a population of cancer cells with additional resistance often emerges, presenting critical challenges that need to be addressed." (PMID 39897079, 2024). "Targeted inhibition of EGFR expression has demonstrated anti-cancer effects in TNBC." (PMID 38699644, 2024).
cancer (continued). "Both PIK3R1 and EGFR were involved in anti-cancer drug effects." (PMID 39190284, 2024). "Additionally, previous studies reported that ESCC-associated proteins, including PCNA, SLC7A5, CTTN, RB1, EGFR, TP63, and PRMT1, exhibited increased expression in S-III; among these proteins, SLC7A5 and EGFR were FDA-approved drug targets for cancer treatment." (PMID 38652547, 2024). "In addition, males have presented fewer side effects than females in clinical trials, and two treatment/cancer type combinations drive favourable SOR outcomes in females: EGFR inhibitors in NSCLC and rituximab in NHL." (PMID 38594230, 2024). "Apoptosis in OVCAR3 cells can potentially be induced by RA via the EGFR pathway, and RA may be a potent agent for cancer therapy." (PMID 38324801, 2024). "EGFR fusion represents a novel oncogenic driver across different cancer types." (PMID 39054543, 2024). "EGFR-targeting nanobody 7D12 have been used for targeted delivery, and together with their smaller size, the 25-nm NPs can penetrate deeper into spheroids and kill cancer cells more efficiently." (PMID 38399272, 2024). "Luteolin has the ability to efficiently suppress cancer-cell growth, and its anticancer activity may be partially derived from inhibitory effects on EGFR-mediated cell survival." (PMID 38474604, 2024). "These two generations of EGFR-TKIs inhibit the activation of EGFR by mimicking the structure of ATP and competitively interact with the binding site of the EGFR kinase domain, thereby inhibiting the occurrence of cancer." (PMID 39308869, 2024). "The effect on the target EGFR/ERBB2 and AKT/PKB pathways was confirmed by up-/downregulated proteins that are part of these pathways and that further implicated the whole range of cancer enabling hallmarks." (PMID 39268460, 2024). "Similarly, EGFR is overexpressed on many cells in cancers like non-small-cell lung cancer, and colorectal and breast cancer, where it can be used as a target to direct the drug to cancer cells." (PMID 38804384, 2024). "eBAT is designed to simultaneously target EGFR on solid tumors and uPAR on the vascular and inflammatory tumor microenvironment, thereby targeting cancer cells, as well as the cells that comprise the cancer niche to deliver a catalytic toxin, while minimizing effects on normal tissues." (PMID 39330834, 2024). "Successful preclinical NIR-PIT studies against cancer and cancer-stem like cell antigens have been performed against more than 20 different molecular targets expressed on different cancers including EGFR, HER2, PSMA, CD25, GPC3, mesothelin, CD133, CD44, CEA, DLL3, PD-L1, and others." (PMID 38658501, 2024). "Other findings, such as FGFR2 fusions, EGFR mutations, or MET exon 14 alterations, may also help refine diagnoses, as they are highly enriched in specific cancer types." (PMID 37682776, 2024). "However, the specific impact of nitrosamine impurities on the modulation of these G-protein coupled signaling pathways and EGFR pathways is yet to be investigated vividly through in vitro and in vivo studies for their potential role in incidence of cancers." (PMID 38799236, 2024). "Aberrant EGFR activation through gene amplification and/or mutation, though common in various types of cancer, is not frequently found in HCC." (PMID 38473265, 2024). "Moreover, when human endothelial cells were incubated with MES-GSC EVs, they became positive for GBM-specific mutant EGFRvIII mRNA and protein expression further enforcing the notion that endothelial cells express oncogenic EGFR received from cancer cells." (PMID 38570528, 2024). "In addition to the role of EGFR in cancer biology, the mechanistic target of rapamycin (mTOR) signaling is a major pathway that mediate a wide variety of cellular physiological processes, such as apoptosis, autophagy, amino acid metabolism, and proliferation." (PMID 38560690, 2024).